TEX13A (testis expressed 13A)
Description:
Binds to ssRNA containing the consensus sequence 5'-AGGUAA-3'. Plays a role in transcriptional repression (By similarity). Required for rapid sperm motility and timely degradation of mRNA via its interaction with CNOT1 (By similarity).
Tractability: No criterion of Open Targets' tractability assessment is met for any kind of drug.
Gene: Protein-coding gene on chromosome X (105,218,929 to 105,220,694, reverse strand). Ensembl gene ENSG00000268629.
Gene Ontology:
Molecular function: protein binding
Homologues: Orthologues: chimpanzee TEX13A (98% identical), macaque TEX13A (92% identical), Drosophila melanogaster CG14718 (14% identical). Paralogues in human: TEX13B (40% identical), TEX13D (27% identical), TEX13C (25% identical).
Diseases named in the same sentence as TEX13A in open-access papers:
TEX13A is named in the same sentence as 1 disease in open-access papers, as found by Europe PMC text mining. Sharing a sentence is not in itself a finding about the gene and the disease.
TEX13A shares sentences with these, for which no sentence is quoted: Infertility (1 paper).